CTLA4 (cytotoxic T-lymphocyte associated protein 4)
Diseases named in the same sentence as CTLA4 in open-access papers (continued):
Sharing a sentence is not in itself a finding about the gene and the disease.
tumor (continued). "Anti-PD-1 and anti-CTLA-4 antibodies could be used to increase the synergistic therapeutic efficiency for distant tumor suppression after treatment with the Au/Ag NRs and NIR-II laser irradiation." (PMID 35630880, 2022). "respectively showed that administration of anti CTLA-4 between intervals of chemotherapy or after radiotherapy and surgery offered effective multimodal anti-MM therapeutics, successfully boosting the anti-tumor response." (PMID 36685577, 2022). "We next examined whether VSV∆51-amiR-4 has better anti-tumour efficacy when combined with anti-CTLA4." (PMID 35393414, 2022). "Currently, numerous ICIs, such as anti-PD-1 (nivolumab or pembrolizumab), anti-PD-L1 (atezolizumab, avelumab, or durvalumab), and anti-CTLA-4 (ipilimumab or tremelimumab) antibodies, can activate the anti-tumor immune response and inhibit the growth of tumor cells." (PMID 36110551, 2022). "Positive correlations were observed between levels of different immune checkpoint-expressing CD4+ T cells, including PD-1, TIM-3, LAG-3, and CTLA-4 with FoxP3+ Tregs, Helios+ T cells, FoxP3+Helios+ Tregs, and FoxP3+Helios− Tregs in the tumor microenvironment (TME)." (PMID 35455287, 2022). "RIG-I activation and CTLA-4 blockade can prime and activate cytotoxic T cells to kill tumour cells." (PMID 35998812, 2022). "Moreover, patients with higher m6ASig score were associated with higher microsatellite instability (MSI); higher PD-L1, CTLA4, and ERBB2 expressions; and greater tumor mutation burden (TMB)." (PMID 36193316, 2022). "Combining conventional immune checkpoint inhibition of CTLA‐4 and PD‐1 may enhance the Treg depletion within the tumor and further potentiate the CD4+ and CD8+ antitumor immunity." (PMID 35782339, 2022). "Under inflammatory conditions, neutrophils release a variety of cytokines, one of which is CXCL12, which was significantly elevated in tumor supernatant from B16.BL6-bearing mice that had been treated with anti–CTLA-4 and 7HP349, for which chemokine receptor CXCR4 is expressed on CD8+ Teffs." (PMID 35552271, 2022). "Anti-PD-1 or anti-CTLA4 therapy inhibited tumor growth, in keeping with prior findings." (PMID 36465373, 2022). "In 1996 Dr James Allison’s team showed that blockade of CTLA-4 could lead to enhanced anti-tumour immune response and tumour rejection." (PMID 33451015, 2021). "Furthermore, the enhanced expression of PD-L1 or other inhibitory ligands such as CTLA-4 on cells within the tumor often restrains the effector functions and the activation of T cells." (PMID 34960142, 2021). "To predict the sensitivity to ICIs between low- and high-risk groups as classified by the GDPLichi model, we further examined immunotherapy-related markers such as tumor mutation burden (TMB), neoantigen, and expression of PDCD1 (PD-1), CD274 (PD-L1), and CTLA4." (PMID 34970479, 2021). "However, they are clearly radioimmunogenic, since they respond very well to radiation therapy plus anti-CTLA4, and provide an excellent model of local and distant tumor control by experimental immunotherapies." (PMID 33816320, 2021). "Chemokines involved in the recruitment of multiple immune cell subsets (Cxcr4, Cxcl13, Ccl22) were upregulated in parallel with the co-stimulatory molecules Icos and the checkpoint receptor Ctla4, suggesting complex immunological changes in the tumor microenvironment (TME) in response to treatment." (PMID 34445452, 2021). "Reports of the expression of CTLA-4 and CD28 in tumor-infiltrating NK cells suggest that further efforts are needed to assess whether the NK cell-specific effects of anti-CTLA-4 blockade have been misattributed to T cells." (PMID 33468555, 2021). "Likewise, in patients with metastatic prostate cancer, anti-CTLA-4 induces anti-tumour TH1 cell-type CD4+ T-cell responses in primary tumours, but this same response is absent in bone metastatic lesions." (PMID 33262520, 2021). "HT also increased PD-L1, CTLA4, and other immune checkpoints within the tumor microenvironment." (PMID 33391491, 2021).
tumor (continued). "PD-L1 and CTLA-4 expression by tumour cells in CRC could cooperate with each other in enhancing tumour progression leading to poor patient outcome." (PMID 35047074, 2021). "As a result, the use of anti-CTLA-4 antibodies during initial autologous OC TIL culture could favour expansion of tumour-reactive CD8+ T-cells in TIL populations and provide a more robust anti-tumour response." (PMID 34944851, 2021). "However, the interaction of mouse CTLA-4 with CD80 has been reported to outcompete the tumor-suppressive CD80 and PD-L1 in cis interaction." (PMID 33923750, 2021). "The expression of CTLA-4 in tumor stem cells was significantly higher than that in tumor cells." (PMID 34553071, 2021). "Consequently, anti CTLA-4 and anti-PD-1/L1 have been established in multiple tumor types such as melanoma, lung cancer, urothelial carcinoma, renal cell carcinoma, esophagogastric cancer, and MSI-high colorectal cancer." (PMID 33919570, 2021). "Anti-PD1 treatments are considered to be more favourable than anti-CTLA-4 treatments in certain tumour types due to their better safety and tolerability profiles, as well as having potential biomarkers for patient stratification and predictions for clinical outcome." (PMID 33923305, 2021). "Targeting the immune checkpoint molecules programmed death 1 (PD-1), programmed death ligand 1 (PD-L1), and cytotoxic T lymphocyte antigen-4 (CTLA-4) leads to reinvigoration of anti-tumor immune responses in cancer patients and, consequently, improved clinical outcomes." (PMID 33710604, 2021). "In the past few decades, studies in the field of cancer immunotherapy have been mainly focused on CTLA-4 and PD-1/PD-L1 blockade, However, since the complex interactions between tumor immune modulators, targeting PD-1/PDL-1 alone might be insufficient." (PMID 33721026, 2021). "Combination therapy with BEMPEG and anti‐CTLA‐4 was especially effective, preventing significant tumor outgrowth of established primary tumor in 100% of treated animals in the DLM8 model for up to 141 days posttreatment initiation, with 100% surviving animals of which 60% were tumor free." (PMID 33152115, 2021). "Thereby, these cases were not under the immune suppressive effect of tumour-associated CTLA-4 expression." (PMID 35047074, 2021). "Moreover, interaction between anti-CTLA-4 antibodies and CTLA-4 on tumor cells results in activation of the EGFR pathway, which leads to increased PD-L1 expression." (PMID 34208339, 2021). "PD-1 and CTLA-4 are expressed on T cells during priming and activation, while in the tumor microenvironment (TME), local interferon-gamma (IFNγ), mainly derived from effector lymphocytes, induces the expression of PD-L1 on cancer cells and intra-tumoral immune cells." (PMID 33541368, 2021). "Given that anti-CTLA-4 therapy and anti-PD-1/PD-L1 therapy only benefits a fraction of patients because of the immunosuppressive tumor microenvironment, there are ongoing efforts to reverse immune suppression and create a more favorable microenvironment for ICIs." (PMID 34367111, 2021). "Cytotoxic T-lymphocyte- associated antigen-4 (CTLA-4), programmed cell death-1 receptor (PD-1), and T-cell inhibitory receptor (TIM-3) are expressed on T-cells and mediate inhibitory effects by interacting with their ligands on tumour cells or TAMs." (PMID 35201470, 2021). "In another similar study, the neutralization of soluble NKG2D ligands such as MICA and MICB with mAb B10G5 was effective against prostate cancer and its metastases, leading to increased infiltration with NK cells to tumor parenchyma and improving CTLA-4 blockade therapy." (PMID 34768814, 2021). "Interestingly, combined CTLA-4+ TILs and PD-L1+ in tumor cells showed better sensitivity for predicting prognosis of ICCs in terms of OS and cumulative recurrence than that of overexpression of either CTLA-4 or PD-L1 alone." (PMID 34526987, 2021).
tumor (continued). "This may be related to the dual inhibitory effects of PD-1/PD-L1 and CTLA-4 pathways, which enhance the anti-tumor efficacy." (PMID 33716732, 2021). "PD-1 and CTLA-4 are the main checkpoints that tumor cells use to block immune system." (PMID 33757216, 2021). "Thus, treatment with the clinical GR antagonist mifepristone can sensitize ICB-refractory PDAC to anti-CTLA-4 and anti-PD-l antibodies, resulting in not only substantial tumor growth inhibition but also significant survival benefit." (PMID 34873175, 2021). "For example, the tumor cell glycolytic rate is depressed by anti-PD-L1 therapy, and patients with low glucometabolic levels in tumors may benefit from CTLA-4 blockade." (PMID 34526987, 2021). "On the other hand, there is significant association between low CTLA4 tumor expression and good prognostic parameters as low tumor stage (T1) and absent vascular invasion." (PMID 33906311, 2021). "Immune targets such as PD-L1, PD-1, and CTLA-4 have been shown to be effective in a variety of tumors, and targeting immune cells to activate checkpoints has been shown to be the most effective way to activate anti-tumor immune responses." (PMID 34899858, 2021). "Tumour infiltrating CD8+ T cells expressed high levels of PD-1 and CD4+ T cells expressed FoxP3 and CTLA4, suggested that immune suppression in the tumour microenvironment may be responsible for downregulation of cytotoxic T cell activity in the tumour." (PMID 34359633, 2021). "In addition, in the MC-38 colon cancer model, the hydrogel loaded with CTLA-4 produced the same degree of tumor growth inhibition as in the CT26 model." (PMID 34842684, 2021). "Common immune checkpoints in the tumour are PD-1/PD-L1 and CTLA-4." (PMID 34419152, 2021). "Moreover, combining EGFR inhibitor ES-072 with anti-CTLA4 immunotherapy results in an additive effect on both tumor growth and cytotoxic T cell activation." (PMID 33879767, 2021). "However, some studies have shown that enhanced tumor therapy via anti-CTLA-4 antibody is dependent on interactions with Tregs and T effectors." (PMID 34194437, 2021). "Notably, a further decrease of tumor growth and even complete regression was observed when ES-072 and anti-CTLA4 treatments were combined." (PMID 33879767, 2021). "Tumor infiltrating Tregs express much higher CTLA-4 than other T cells." (PMID 34806028, 2021). "CTLA4 is expressed in normal tissues, normal immune cells, and tumor cells simultaneously." (PMID 33842369, 2021). "After 9 days, the tumor‐bearing mice were treated with anti‐PD‐1 or anti‐CTLA‐4 antibodies." (PMID 33934451, 2021). "Furthermore, the expression of SLC13A4 in HNSCC is negatively correlated with a variety of T cell exhaustion markers, including LAG3 ( p < 0.001), TIM-3( p < 0.001) and CTLA-4 ( p < 0.001), indicating its potential mechanism in regulating tumor immunity." (PMID 34840533, 2021). "Notably, tumor growth has been retarded upon CD80 knockout or antibody-mediated blockade of either CD80 or CTLA-4." (PMID 33430105, 2021). "However, concurrent application of the anti-CTLA-4 and anti-PD-1 molecules appeared to markedly inhibit the formation of the in vitro colonies by the tumor cells obtained from the lungs of the i.v.- or o.t.-injected mice." (PMID 34208396, 2021). "To this end, we developed a novel chimeric receptor that can recognize CD80 and CD86 as tumor antigens on malignant B cells by combining the extracellular and transmembrane domains of CTLA4 with the intracellular signaling domains of CD28 and CD3z and explored its potential in cancer treatment." (PMID 33868277, 2021). "Interestingly, CTLA4-inhibitors are in clinical use as immunotherapeutics for their function of activating host immune response against tumours." (PMID 34331199, 2021).
tumor (continued). "Furthermore, cotreatment of syngeneic mouse tumor models with the HDACi entinostat and 5-azacytidine markedly improved the response to both anti–PD-1 and anti–CTLA-4 checkpoint inhibitor antibodies, curing more than 80% of the tumor-bearing mice." (PMID 34001289, 2021). "A limited exploration of alternate clinically relevant components in the priming regimen suggested that the anti-PD-1 in AIP can be replaced with anti-CTLA-4, whereas switching “A” or “I” with anti-CTLA-4 elicited decreased therapeutic efficacy depending on the tumor model." (PMID 34818534, 2021). "Therapies such as anti-CTLA4 antibodies, that block CTLA4 function have an anti-tumour effect." (PMID 34683450, 2021). "Tumor growth was significantly decreased both by the ES-072 treatment and the anti-CTLA4 treatment." (PMID 33879767, 2021). "Shin et al7 reported that the cytotoxic T-lymphocyte-associated protein 4 (CTLA4)-CD28 chimera, consisting of the extracellular and transmembrane domains of CTLA4 and the cytoplasmic domain of CD28, enhanced the activity of tumor-specific T cells." (PMID 34853180, 2021). "Based on the preclinical studies, MEK inhibitors could improved T cell activation, conditioned the tumor microenvironment to facilitate improved response to anti-CTLA-4 treatment and prolonged survival in KRAS-mutant mice in combination with CTLA-4 blockade." (PMID 33402199, 2021). "Many studies have suggested that increasing oxygen in the TME could improve the anti-tumor efficacy of PD-1/PD-L1 and CTLA-4 antibodies." (PMID 34895169, 2021). "In the TME, CTLA-4 inhibits immune response and promotes tumor cell survival." (PMID 34868991, 2021). "CTLA-4+ tumor-infiltrating Tregs could also contribute to tumor immune evasion by suppressing antitumor immunity and downregulating CD80/86 expression on APCs." (PMID 34868991, 2021). "In the case of possible hyperprogression, a high baseline serum LDH and diffuse metastatic spread were observed, which might suggest aggressive tumor biology before the initiation of anti-PD1 + anti-CTLA4." (PMID 32929554, 2021). "To date, there are several biomarkers being studied that may help to predict the benefit of CTLA-4 and PD-1/PD-L1 inhibition, including PD-L1 expression in tumor and immune cells and high TMB in patients with dMMR, MSI-H or HR deficiency." (PMID 33946818, 2021). "However CTLA-4 inhibitors can inhibit the molecule CTLA-4, allowing T cells to proliferate and attack tumor cells." (PMID 34759817, 2021). "Although some reports have suggested that the depletion of Tregs is the primary reason for the antitumor response in CTLA-4 blockade, it is likely that both effector/memory T cell activation in SLOs and Treg depletion in tumor tissue cooperatively exert antitumor responses." (PMID 34572844, 2021). "While, CMS1 tumors exhibit potent anti-tumor activity, transcription of genes encoding ICs such as PDCD1, CD274, CTLA4, and LAG3 may aid tumor immune escape in these tumors." (PMID 33477864, 2021). "When combined with CTLA-4 inhibitors, the ratio of Treg/CTL within the tumor decreased significantly, and the release of inflammatory factors increased, which eventually caused the inhibition of distant tumor growth." (PMID 33784955, 2021). "However, concomitant depletion of CAF and blocking of CTLA-4 decreased tumor growth and prolonged survival of PDAC bearing mice." (PMID 34638420, 2021). "Theseantibodies include the well‐publicized checkpoint inhibitors such as anti‐CTLA‐4, which may also derive some therapeutic effect from thedepletion of Tregs within the tumour environment." (PMID 33638871, 2021). "We hypothesized that CTLA-4 play roles in modulating DEGs in Treg from normal tissues, non-tumor diseased tissues and tumor tissues." (PMID 34084175, 2021). "CTLA-4 blockade has shown efficacy in a number of preclinical tumor models (reviewed in 80)." (PMID 34025662, 2021).
tumor (continued). "Moreover, the present results detected a positive relationship between PD-L1 expression and CTLA-4 expression in tumour cells (p < 0.001)." (PMID 35047074, 2021). "CTLA4, Tim3, Foxp3, GATA3, CD127, TCRab and TIGIT increased in cluster 17 of CD3+ T cell in patients with LC, of which CTLA4 expressed in tumour CD8 T cells associated with PD‐1‐mediated T‐cell dysfunction and efficacy of the checkpoint block immunotherapy in cancers." (PMID 34841705, 2021). "Furthermore, CTLA4-targeted NIR-PIT induced an abscopal effect in over half of the tumor-bearing mice." (PMID 34064074, 2021). "ICI are monoclonal antibodies that target these immune-inhibitory molecules, expressed by T-cells, such as CTLA-4 and PD-1, as well as the PD-1 ligand expressed by tumor cells but also epithelial cells and others in physiological conditions, resulting in enhanced immunity and often autoimmunity." (PMID 33897597, 2021). "Furthermore, we analyzed tumor-infiltrating lymphocytes and found that during chemotherapy, the proportions of CTLA4+ cells and PD-1+/CTLA4+ cells in CD8+ T cells slightly increased after cavitation treatment." (PMID 34271256, 2021). "Therefore, α-IL-6 and α-CTLA-4 combination treatment led to effective and long-lasting anti-tumor activity." (PMID 34093869, 2021). "In another mouse study, the timing of 20 Gy × 1 fraction and anti-CTLA4 antibodies reported that the best tumor control and survival advantage was observed in the group that started the anti-CTLA4 antibodies before radiotherapy, compared with the group that started it after radiotherapy." (PMID 33561212, 2021). "PD1, PD‐L1, and CTLA‐4 are important immune checkpoints responsible for tumor immune escape." (PMID 34453499, 2021). "Indeed, STING-deficient mice were unable to respond to anti-PD-1 and anti-CTLA-4 in B16F10 melanoma model, and cGAMP administration along with ICB inhibited tumor and metastasis formation and delayed tumor growth." (PMID 34925363, 2021). "Recently, a number of studies suggested that tumor cell-intrinsic CTLA4 might execute different functions, from inducing apoptosis to regulating cell proliferation, than that of T cells." (PMID 35096593, 2021). "Since adding the CTLA-4 inhibitor ipilimumab has already shown anti-tumor activity in PD-1-refractory patients with metastatic MCC, combined ICB according to the ongoing CheckMate-358 study (NCT02488759) seems to be a promising treatment option for avelumab-refractory patients." (PMID 33439294, 2021). "(I–K) Flow cytometric analysis of the expressions of programmed cell death-1(PD-1) (I), PD-1 and Tim3 (J), and CTLA-4 (K) in CD8+ T cells in the tumor of Cd300afl/fl (n = 4 in I, n = 3 in J and K) and Cd300afl/fl;ItgaxCre (n = 6 in I, n = 5 in J, n = 4 in K) mice." (PMID 34751648, 2021). "CTLA4 was reported to inhibit the immune response at the initial stage of T-cells activation, while PD-1 downregulates ongoing immunological effects at sites of reaction, either in the tumor tissue or in the peripheral blood." (PMID 37305162, 2021). "Therapy resistance, e.g. against cytostatic drugs, but also immunotherapies such as cytotoxic T-lymphocyte-associated protein 4 (CTLA-4) inhibitors, is still a major clinical challenge in the treatment of PDAC patients, and has been related to tumor heterogeneity implying the presence of CSCs." (PMID 34631577, 2021). "The effect of the combination therapy was higher with anti-CTLA4 than with anti-PD-1, and cumulatively affected 100% of the mice (3/5 CR and 2/5 PR), highlighting that the response needed to be determined as a function of tumor specificities." (PMID 34696515, 2021). "Furthermore, we did not observe a significant impact of the depletion of NK1.1+ cells or macrophages on the efficacy of CTLA-4 blockade although this treatment has been shown to induce the activation and degranulation of tumor-infiltrating NK cells." (PMID 33923750, 2021). "CTLA-4 blockade stimulates anti-tumor immunity of T cells and inhibits tumor growth." (PMID 34203292, 2021).